EPDR1 (ependymin related 1)
Diseases named in the same sentence as EPDR1 in open-access papers (continued):
Sharing a sentence is not in itself a finding about the gene and the disease.
tumor (17 papers, 2014 to 2025). "The results of living-imaging showed that EPDR1 overexpression caused a significant reduction in tumor burden." (PMID 35004274, 2021). "Furthermore, EPDR1 expression was associated with tumor-infiltrating immune cells (TIICs), including NK cells, CD8 + T cells, CD4 + T cells, Macrophages cells, and so on." (PMID 33902536, 2021). "To investigate the underlying molecular mechanism that was involved in the tumor suppressor role of EPDR1, we examined whether miRNAs could regulate EPDR1 levels in EOC patients." (PMID 35004274, 2021). "Next, we focused on the underlying mechanism by which EPDR1 inhibits tumor progression." (PMID 35004274, 2021). "Moreover, EPDR1 hypermethylation was significantly correlated with node negativity and a lower tumor stage as well as with mutations in B-Raf proto-oncogene serine/threonine kinase (BRAF) and human transforming growth factor beta receptor 2 (TGFβR2)." (PMID 30360391, 2018). "These facts may be the cause of the involvement of EPDR1 with tumour development in vivo." (PMID 32111877, 2020). "Collectively, our study reveals a previously unappreciated role of EPDR1 in orchestrating tumor immune evasion and cancer progression." (PMID 39152265, 2024). "Additional flow cytometry analysis unveiled that the suppression of EPDR1 in cancer cells led to a reduction in exhaustion and an increase in the activation of tumor-infiltrating T cells in mice (Fig. EV2J,K)." (PMID 39152265, 2024). "To investigate the role of EPDR1 in regulating CD8+ T-cell-dependent tumor immune evasion, we performed qRT-PCR analyses on a series of immune-related molecules in HepG2 cells." (PMID 39152265, 2024). "Using HCC mouse models, we found that tumor-intrinsic EPDR1 promotes CD8+ T-cell exhaustion by elevating the transcriptional level of PD-L1." (PMID 39152265, 2024). "Upon extraction of tumor cells from the xenografts, we observed that EPDR1 knockdown in Hepa 1–6 cells significantly attenuated PD‐L1 cell surface expression (Fig. EV3D)." (PMID 39152265, 2024). "To further demonstrate that PD-L1 is a functional EPDR1 target, we inoculated mEPDR1 or EV overexpressing Hepa 1–6 cells with PD-L1 knockdown into mice and detected tumor-infiltrating CD8+ T-cell exhaustion and activity markers." (PMID 39152265, 2024). "Taken together, these findings supported the notion that EPDR1 played a role of tumor suppressor in EOC progression." (PMID 35004274, 2021). "In our study, we found that EPDR1 was downregulated in EOC tissue samples, and low EPDR1 was associated with tumor progression and poor prognosis in EOC patients by analysis of TCGA, GTEx, GEO and CPTAC dataset, RT-PCR, Western blot, and IHC." (PMID 35004274, 2021). "In conclusion, our study validated that EPDR1, negatively regulated by miR-429, played an important role as a tumor-suppressor gene in EOC development via inhibition of the PI3K/AKT pathway." (PMID 35004274, 2021). "As mentioned in the present work and published paper, EPDR1 overexpression functions to degrade tumor progression." (PMID 34218800, 2021). "In summary, these results demonstrate that the inhibition effect of EPDR1 on tumor progression is regulated by miR-429 through PI3K/AKT pathway." (PMID 35004274, 2021). "In other words, the expression of EPDR1 in the environment of the tumour tissues seems to be a better predictor of survival time than the expression in the tumour itself." (PMID 32111877, 2020). "Expression of total EPDR1 is detected in normal mucosa at a very low level, but is clearly expressed in almost all the tumour samples." (PMID 32111877, 2020). "When compared with normal mucosa, the gene is significantly up-regulated in tumour tissues and a significant relationship has been observed between EPDR1 expression and TNM staging parameters of cancer, especially T and M stages." (PMID 32111877, 2020).
tumor (continued). "The dependence of the survival time on EPDR1 expression in tumours is close to significance (p = 0.085), but a very significant dependence was observed with respect to the expression of the gene in the histologically normal tumour borders (p = 0.0057)." (PMID 32111877, 2020). "The comparison of the paired samples included in the TCGA cohort (n = 50) also allowed us to conclude that EPDR1 expression is significantly higher in tumour than in paired adjacent mucosa." (PMID 32111877, 2020). "Both statistical and functional analysis correlated EPDR1 overexpression with invasiveness and dissemination of tumour cells, supporting the inclusion of EPDR1 in panels of genes used to improve molecular subtyping of CRC." (PMID 32111877, 2020). "We first determined the means of EPDR1 mRNA expression, measured by RT-qPCR, in 97 paired tumour and normal samples from the 101 patients’ cohort." (PMID 32111877, 2020). "In summary, the analysis of expression data in a large number of patients, both in vivo and in silico, allowed us to conclude that EPDR1 is significantly up-regulated in tumour tissues when compared to adjacent mucosa." (PMID 32111877, 2020). "In addition, we demonstrated that overexpression of EPDR1 down-regulated the expression of interstitial-related proteins in BC cells and inhibited tumor growth in vivo." (PMID 38308220, 2024). "Considering the crucial role of PD-L1 in facilitating immune evasion by tumors, we hypothesize that EPDR1 modulates immune cell activity through the regulation of PD-L1 expression in tumor cells, potentially promoting immune evasion." (PMID 39152265, 2024). "Moreover, we conducted an in vitro coculture experiment to explore the direct impact of EPDR1 upregulation in tumor cells on the phenotype and function of CD8+ T cells." (PMID 39152265, 2024). "We conducted immunohistochemistry of EPDR1 in tumor tissues." (PMID 36276104, 2022). "All tumor tissues were subjected to immunohistochemistry for EPDR1." (PMID 36276104, 2022). "EPDR1 expression and tumor-infiltrating immune cells (TIICs)." (PMID 33902536, 2021). "As expected, overexpression of EPDR1 remarkedly reduced the tumor volume and weight." (PMID 35004274, 2021). "We also compared the expression of EPDR1 in tumor and paracancerous tissues from the same patient." (PMID 32935479, 2020). "Since the results showed that EPDR1 expression was very low in various immune cell clusters, we speculate that HCC cells‐derived EPDR1 might modulate immune cell infiltration into the tumor microenvironment in a paracrine manner." (PMID 32935479, 2020). "The dissemination of cancer cells may be facilitated by the effects of EPDR1 on adhesion to type I collagen fibres, which have been described as the “highways” for tumour cell migration." (PMID 32111877, 2020). "In addition, relationship between EPDR1 expression and tumor‐infiltrating immune cells, as well as immune‐related genes was explored through multi‐dimensional analysis." (PMID 32935479, 2020). "Additionally, three independent microarray studies obtained from the GEO database validated the significant higher expression of EPDR1 in tumor tissues than in the normal tissue." (PMID 32935479, 2020). "Interestingly, EPDR1 hypermethylation was significantly correlated with node negativity (p = 0.044) and an early tumor stage (p = 0.044)." (PMID 30360391, 2018). "We found that the level of EPDR1 mRNA was significantly lower in tumor tissues than in corresponding normal tissues (p < 0.001), whereas the methylation level of EPDR1 in 23 tumor tissues was significantly higher than that in corresponding normal tissues (p < 0.001)." (PMID 30360391, 2018). "The present study demonstrated that EPDR1 hypermethylation is significantly correlated with a negative node status, a lower tumor stage, BRAF and TGFβR2 mutations and better prognosis in CRC patients." (PMID 30360391, 2018). "Similarly, EPDR1 knockdown significantly attenuated tumor growth." (PMID 39152265, 2024).
tumor (continued). "Similarly, in the nude mouse model, overexpression of EPDR1 inhibited tumor growth and metastasis." (PMID 38308220, 2024). "Additionally, we explored the inhibitory function on the tumor invasion of EPDR1 in CRC cells." (PMID 30360391, 2018). "Here, we identified ependymin-related protein 1 (EPDR1) as an important tumor-intrinsic regulator of PD-L1 expression and tumor immune evasion." (PMID 39152265, 2024). "To enhance our insights into the prognostic validity of the five-gene signature, we examined the expression of ATP6AP1, SLC7A5, EPDR1, SDC1, and PIGR in 13 paired BC samples, comparing them with their adjacent non-tumor tissues through RT-PCR." (PMID 38162504, 2023). "To further address the role of EPDR1 in EOC progression, we generated subcutaneous xenograft tumor mouse models of EOC." (PMID 35004274, 2021). "We found that EPDR1 expression had a significant difference in BLCA and adjacent normal bladder tissues, and the level of EPDR1was up-regulated with advanced tumor stage and metastasis in BLCA." (PMID 33902536, 2021). "All in all, we demonstrated that EPDR1 was downregulated in EOC tissues, and low EPDR1 expression was correlated with tumor stage, lymph node and distant metastasis, and poor prognosis." (PMID 35004274, 2021). "All these results manifest that a strong relation exist between EPDR1 expression in CRC tissues and the invasiveness of tumour cells." (PMID 32111877, 2020). "Five aberrantly methylated genes (epidermal growth factor, EGF; carbohydrate sulfotransferase 10, CHST10; ependymin related 1, EPDR1; bone marrow stromal antigen 2, BST2; and Rac family small GTPase 3, RAC3) were further verified in CRC tumor tissues." (PMID 30360391, 2018). "We performed qPCR on a subset of genes that were either among the most significant DEGs identified in our analysis of colon organoids of FAP versus healthy subjects and/or were significant in an analysis of either EOCRC tumor datasets: NKD1, EYA2, EGR2, EPDR1 and IGFL1." (PMID 36077675, 2022). "The expression on Box Plots of EPDR1 in BLCA was conducted from GEPIA and the expression data are first log2(TPM + 1) transformed for differential analysis where the log2FC is defined as median (Tumor) – median (Normal)." (PMID 33902536, 2021). "When a Cox regression including the AJCC stage was carried out, the survival time was also found significantly dependent on the EPDR1 expression in tissues adjacent to the tumour (p = 0.0344) but not on the expression in the tumour itself (p = 0.1161)." (PMID 32111877, 2020). "It is worth noting that patients’ survival depends more on the expression of EPDR1 in non-tumour adjacent mucosa than in tumour itself." (PMID 32111877, 2020). "Meanwhile, EPDR1 low expression was significantly related to FIGO stage (P = 0.0021), lymph node status (P = 0.0041), and distant metastasis (P = 0.002) but not to age, tumor size, or histological type." (PMID 35004274, 2021).
cancer (13 papers, 2017 to 2025). A tumor composed of atypical neoplastic, often pleomorphic cells that invade other tissues. "Although the function of EPDR1 has not been completely characterized, accumulating evidence suggests that EPDR1 is associated with various human diseases, particularly the initiation and progression of various human cancers." (PMID 35004274, 2021). "In recent years, a growing number of studies have been performed to demonstrate the association of EPDR1 and cancers." (PMID 35004274, 2021). "Notably, the number of surviving decreased, and cancer-related death increased with increasing risk scores, thus the group with high EPDR1 expression seemed as having a shorter OS compared to the low or medium expression-group." (PMID 33902536, 2021). "EPDR1 was associated with multiple signaling, as well as cancer and apoptotic pathways." (PMID 32935479, 2020). "EPDR1 was ultimately chosen as the subject of our research due to the limited studies on cancer immunity." (PMID 39152265, 2024). "It implied that EPDR1 exerts its effect on PD-L1 expression through modulation of the NF-κB signaling pathway in cancer cells." (PMID 39152265, 2024). "EPDR1 function remains poorly characterized, although it has been recently shown to modulate cell migration and invasion of cancer cells." (PMID 35872017, 2022). "After overexpressing EPDR1, the cancer-promoting effect of miR-429 was partially repressed, which suggested the presence of additional targets of miR-429 in EOC." (PMID 35004274, 2021). "Although few studies to date have investigated EPDR1 expression in cancer cells, it is highly expressed in CRC cells." (PMID 30360391, 2018). "Although few studies have reported EPDR1 expression in cancer cells, EPDR1 is known to be highly expressed in CRC." (PMID 30360391, 2018). "Recent studies also suggest that EPDR1 exhibits aberrant expression in various cancers." (PMID 39152265, 2024). "The different roles of EPDR1 gene in diverse cancers could be attributed to the epigenetic silence due to DNA methylation." (PMID 35004274, 2021). "According to the expression levels of EPDR1, we divided the cancer cases into 2 (By median), or 3 groups (By tertiles): low-expression, medium-expression, and high-expression and we explored the correlation of EPDR1 expression with the prognosis of patients with BLCA." (PMID 33902536, 2021). "Thus it suggested that EPDR1 expression with the infiltration levels of various immune cells may play a role in modulating cancer immunity." (PMID 33902536, 2021). "Other genes, such as EPDR1 and HOXA11–AS, identified as critical factors for cancer growth and metastasis, warranted further investigation in the context of AML." (PMID 39335660, 2024). "Our study indicated that EPDR1 expression significantly correlates with the infiltration levels of various immune cells in the TME of HCC, suggesting a role of EPDR1 in modulating cancer immunity." (PMID 32935479, 2020).
skin disorder (1 paper, 2022). Any deviation from the normal structure or function of the skin or subcutaneous tissue that is manifested by a characteristic set of symptoms and signs. "One such factor is EPDR1, which may represent a therapeutic target for the regulation of aging-related skin disorders." (PMID 36497009, 2022).
EPDR1 also shares sentences with these, for which no sentence is quoted: metabolic disorders (2 papers); osteoporosis (2); bladder tumor (1); exfoliation syndrome (1); fatty liver disease (1); Hyperinsulinemia (1); Hypertension (1); pancreatic adenocarcinoma (1); stomach adenocarcinoma (1); type 2 diabetes mellitus (1); urothelial carcinoma (1).